TNF (tumor necrosis factor)
Diseases named in the same sentence as TNF in open-access papers (continued):
Sharing a sentence is not in itself a finding about the gene and the disease.
glioma (continued). "Moreover, intragastric administration of PHOR in a dose of 1.5 g/kg BW to a nude mouse model of glioma remarkably slowed glioma growth and increased the levels of TNF-α, IL-1β, and IL-6 through the activation of PI3K/AKT signaling." (PMID 31281578, 2019). "In addition, our results show a reduction in the levels of proinflammatory cytokines, such as IFN-γ, IL-6, and TNF-α in simvastatin-treated C6 glioma cell line." (PMID 30524484, 2018). "TNF signaling pathway is also an important regulator of the progression of glioma." (PMID 30069164, 2018). "Interestingly, tumor necrosis factor-alpha (TNF-alpha) mediated mesenchymal differentiation of glioma stem cells, in a NF-ĸB-dependent fashion." (PMID 30279357, 2018). "TNF-α, which has been shown to be involved in malignant diseases, had increased expression in the co-cultured glioma cells, which in turn can bind to its receptor on the MCs to activate them, thereby expanding the inflammatory network and facilitating proper establishment of the malignancy." (PMID 28445977, 2017). "Tumor necrosis factor-like weak inducer of apoptosis (TWEAK), a member of the tumor necrosis factor (TNF) superfamily, can stimulate glioma cell invasion and survival via binding to fibroblast growth factor-inducible 14 (Fn14) and subsequent activation of the transcription factor NF-κB." (PMID 28103571, 2017). "Thus, TNF-α enables glioma cells to escape from immune response and grow aggressively in the inflammatory microenvironment." (PMID 28346397, 2017). "In glioma microenvironment TNF-α secretion lead to promotion tumor formation and angiogenesis." (PMID 28346397, 2017). "Similarly, the expression levels of key mesenchymal molecules including YKL40/CHI3L1 and FN1 (FIBRONECTIN 1) in GICs can be greatly induced by TNF-α treatment or overexpressing C/EBPβ, a transcription factor essential in mesenchymal transformation of gliomas." (PMID 27259253, 2016). "Furthermore, VA has been shown to significantly inhibit LPS-induced production of TNF-alpha and IL-6 by human monocytic leukemia and glioma cells." (PMID 26317011, 2015). "While this work calls into question previous studies that have used the B-D13 antibody to assess IL13Rα2 expression, it also suggests that TNF may have significant effects on glioma biology by up-regulating VCAM-1." (PMID 24787244, 2014). "IL-1β is an additional cytokine secreted by glioma cells subsequent to TNF-α treatment." (PMID 25411122, 2014). "Glioma cells treated with TNFα positive control) also showed a strong band for moesin." (PMID 23855374, 2013). "Furthermore, it has been reported that tumor necrosis factor (TNF) dependent action enhances macrophage/microglia recruitment in glioma." (PMID 23983766, 2013). "An analog of thalidomide, CC-5103 increases the secretion of critical cytokines of the tumor microenvironment, including IL-2, IFN-γ, TNF-α, and IL-10, and is currently being evaluated in clinical trials for the treatment of recurrent or refractory pediatric central nervous system tumors." (PMID 23717811, 2013). "Knowledge of the role of TNF-α in human gliomas, however, is limited." (PMID 22190972, 2011). "The IκB-NFκB pathway is involved in TNF-α-induced IL-6 release from C6 glioma cells." (PMID 20205746, 2010). "Therefore, the present study investigated which residue is involved in the TNF-α-stimulated IL-6 synthesis in C6 glioma cells." (PMID 20205746, 2010). "In addition, TNF-α (10 ng/ml) significantly induced IL-6 mRNA expression at 6 h after stimulation, thus suggesting that TNF-α stimulates the synthesis of IL-6 in C6 glioma cells." (PMID 20205746, 2010). "Prior studies suggested that TNFα therapy may be beneficial for the treatment of glioma due to the ability to promote apoptosis, but the sensitivity of cancer stem cells to this effect has not been determined." (PMID 20186265, 2010).
glioma (continued). "Leptin has been shown to induce or to potentiate together with interferon γ (IFNγ), with tumor necrosis factor α (TNFα) or with IFNγ and IL-1β, NO production in murine J774A.1 macrophages, rat adipocytes, C6 glioma cell-line, and rat vascular smooth muscle cells (VSMCs)." (PMID 19688109, 2009). "Moreover, TNFα links inflammation to carcinogenesis through ROS and it was reported that TNFα elevates ROS production in glioma cells." (PMID 20204172, 2009). "Reports on the effects of TNF-α on glioma growth and progression are contradictory." (PMID 17565690, 2007). "In addition, a Kaplan–Meier (KM) survival analysis was conducted on the core genes in liver cancer, renal clear cell carcinoma, and glioma, and it was found that TNF, IL6, IFNG, and NR1H4 in liver cancer and TNF and IL1B in renal clear cell carcinoma were associated with survival prognosis." (PMID 40238193, 2025). "In addition, alcohol may regulate the expression of immunosuppressive cytokines, such as IL-6 and TNF-α, which could affect the glioma microenvironment and inhibit tumor initiation and progression." (PMID 39940440, 2025). "Consequently, a treatment plan that combines temozolomide with EGFR and TNF inhibition may represent an effective therapeutic approach for gliomas expressing CSMD1." (PMID 38561856, 2024). "Consequently, it could be speculated that TNF, which could be secreted by glioma cells after high-dose temozolomide treatment, is a key regulator of inflammation in the TME." (PMID 38561856, 2024). "Interestingly, glioma cell treatment with TNF-α enhances SERT-dependent serotonin uptake and also seems to activate the MAPK signaling pathway, whereas pre-treatment with the MAPK inhibitor SB203580 attenuates the TNF-α-mediated stimulation of serotonin transport." (PMID 37298344, 2023). "Therefore, we hypothesized that the six TNF-related lncRNAs as a prognostic model might also contribute to the discovery of prognosis-related biomarkers in glioma patients." (PMID 37153654, 2023). "In RASF, TNF might enhance catecholamine synthesis not only by increasing TH expression but also by increasing cofactors important for the activity of TH such as tetrahydrobiopterin (BH4) as demonstrated in glioma cells." (PMID 36918850, 2023). "The glioma resection surgery increased the levels of proinflammatory cytokines (e.g., TNF-α, IL-6) in the brain, which promoted the recruitment of systemic administrated ND-MMSNs to the residual glioma site, improved survival rate, and delayed glioma relapse in the surgically treated glioma mice." (PMID 37111742, 2023). "We also found that IDHmt gliomas had a higher proportion of GAMs with an M1‐like phenotype (IDHmt: IDHwt = 90.62%: 75.86%), as supported by an augmented proinflammatory signaling consisting of GAM‐associated cytokines and receptors, such as TNF, TLR2, and TNFRSF1B." (PMID 37166058, 2023). "Similarly, DEX could significantly stabilize hemodynamics, reduce inflammation via the downregulation of serum TNF-α, and inhibit free radical generation, playing a vital role in brain protection in patients undergoing craniotomy resections of glioma." (PMID 36765695, 2023). "The antitumor effects of TNFα include its ability to stimulate T-cell growth and enhance monocyte, granulocyte, and natural killer cell cytotoxicity, at the same time TNFα secretion leads to the promotion of glioma formation and development through angiogenesis." (PMID 36366531, 2022). "Moreover, CK2 regulates glioma cell viability and confers resistance to TNFα-induced apoptosis." (PMID 35214064, 2022).
glioma (continued). "For the upregulated genes in the Ad-SGE-REIC-treated U87ΔEGFR glioma brain tissue compared with the control, 14 significantly enriched pathways were identified, including the Notch Signaling Pathway, IL-2 Signaling Pathway, and TNF-alpha NF-kB Signaling Pathway." (PMID 36006934, 2022). "Therefore, U118MG and U251MG cells were treated with TNFα for up to 4 days to determine whether CHI3L1 expression was dependent on sustained activation of NF-κB pathway in glioma." (PMID 36276655, 2022). "The high expression of TLR3 in lower grade glioma (LGG) and LUSC; FASLG in LGG, UVM, KIRC, and THYM; RIPK3 in LGG, KIRC, and LUSC; RIPK1 in LGG and THCA; FAS in LGG, UVM, and THYM; MLKL in LGG, UVM, and LUAD; FADD in LGG and HNSC; and TNF in UVM and CESC was associated with poor survival." (PMID 35748782, 2022). "Specifically, elevated IRE1 phosphorylation, Tumor Necrosis Factor (TNF) Receptor-Associated Factor-2 (TRAF2) expression, Apoptosis Signal-Regulating Kinase-1 (Ask1) phosphorylation, c-Jun N-Terminal Kinase (JNK) phosphorylation, and Noxa expression appeared in gefitinib-treated glioma cells." (PMID 33920356, 2021). "Therefore, SLC39A7 may activate the TNF-α-mediated NF-κB signaling pathway, thereby promoting the malignant progression of glioma." (PMID 34149917, 2021). "Moreover, TNFα has been reported to increase CXCR4 expression in glioma cells." (PMID 34764346, 2021). "This indicates that TNF‐α may induce IκB degradation and consequently release NF‐κB from inhibitive status, resulting in the nuclear translocation of NF‐κB and rapid cell cycle and proliferation in glioma cells." (PMID 31691497, 2020). "Therefore, we proposed to determine whether WDFY-AS2 affected glioma cell behaviors through regulating glutamate receptor or TNF signaling pathway." (PMID 30069164, 2018). "In addition, studies also showed that TNF-α may produce increased tumor cell growth, invasion, and progression, including gliomas (i.e., a common type of primary brain tumors)." (PMID 30442087, 2018). "Even though TNF-alpha causes recruitment of p65 and p50 subunits of NF-κB to the CHI3L1 promoter in all cell types, recruitment of histone deacetylases (HDAC)-1 and -2, and a consequent deacetylation of histone H3 at the CHI3L1 promoter occurs only in glioma cells." (PMID 26425658, 2015). "Cytokines may also modulate angiogenesis by regulating VEGF expression, for example, tumor necrosis factor (TNF)-α increases VEGF mRNA in glioma cells, and transforming growth factor (TGF)-β results in the induction of VEGF mRNA and protein in human lung adenocarcinoma cells." (PMID 20508816, 2010). "Its ability to upregulate TNF-α, RIP1, RIP3, and MLKL both in vitro and in vivo suggests emodin as a potential anti-cancer agent targeting glioma through necroptosis." (PMID 40490812, 2025). "We found that CM from GL261 or ALTS1C1 mouse glioma cells significantly induced BV2 cells and primary microglial activation by increasing the expression of cytokines such as IL-6 and TNFα." (PMID 41367876, 2025). "This study systematically explored for the first time the combined effect of AVP, OT, β-EP and serum inflammatory factors (TNF-α, IL-6, CRP) in postoperative nerve injury and prognosis of patients with glioma, filling the research gap in this field." (PMID 41244525, 2025). "This is consistent with MeRIP-seq analysis reported by Li and colleagues that showed m6A modification peaks were enriched in the Metabolic, TNF signalling, and PI3K-Akt–related transcripts in glioma stem cells." (PMID 41310336, 2025). "The enrichment analysis revealed that the CNOT7 participated in the development of glioma via G2M checkpoint, E2F targets, IL6-JAK-STAT3, and TNF-α signaling pathways via NF-κB." (PMID 38985240, 2025). "CNOT7 regulates the progression of glioma by affecting the E2F targets, G2/M checkpoint, TNF-α and IL6-JAK-STAT3 signaling pathway through NF-κB, leading to poor prognosis in glioma." (PMID 41249119, 2025).
glioma (continued). "In preclinical glioma models, these triple-edited CAR T cells exhibited enhanced antitumor activity, elevated Th1 cytokine secretion (IFN-γ, TNF-α), and improved persistence following repeated antigen stimulation." (PMID 40895575, 2025). "Immune-related pathways such as TNF signalling (IDH3B/G, MDH1, ACO2, SDHA, OGDHL) and JAK/STAT3 (PIAS2/3, PTPN2, AKT1/2, MCL1, CISH, AOX1) signalling are enriched in gliomas and play a critical role in their progression." (PMID 41007296, 2025). "Conversely, pathogenic bacteria and endotoxins can upregulate cytokines such as IL-6 and tumor necrosis factor alpha (TNF-α), enhancing glioma invasiveness." (PMID 41514614, 2025). "As expected, the conditioned medium from either GL261 or ALTS1C1 glioma cells significantly activated BV2 cells with a notable increase in pro-inflammatory cytokines, including IL-6, CCL-2, CXCL-10, MMP-14, TNFα, IL-1β, and iNOS." (PMID 41367876, 2025). "The analysis of GSEA and GSVA revealed that the CNOT7 participated in the development of glioma via G2M checkpoint, E2F targets, IL6-JAK-STAT3, and TNF-α signaling pathways via NF-κB." (PMID 38985240, 2025). "Both pSTAT3-Y705 and pP65-Ser536 showed enrichment in the nuclear and/or cytoplasmic fractions of Ctrl glioma cells treated with TNF, in contrast to the CSMD1-overexpressing glioma cells." (PMID 38561856, 2024). "In contrast, levels of IL-4, IFN-α, IFN-γ, IL-6, TNF-α, CCL4, P-cadherin, TRAIL, CCL11, and VEGF were significantly higher in serum than in CSF for both glioma and brain inflammation groups." (PMID 39364412, 2024). "The levels of serum factors IL-4, IFN-α, IFN-γ, IL-6, TNF-α, CCL4, CCL11, and VEGF were found to be significantly higher in gliomas compared with inflammatory diseases of the central nervous system (p < 0.05)." (PMID 39364412, 2024). "We also saw increased TNFα, complement, and antigen presentation signaling occurring in high CD83-scored glioma compared with low." (PMID 39601621, 2024). "Using ELISAs and media from our primary mouse glioma cell lines cultured alone or cocultured with naïve CD8+ T cells, we assessed the production of proinflammatory cytokines IL-2, IFNγ, and TNFα." (PMID 39601621, 2024). "Resveratrol demonstrates anti-tumor effects in gliomas by significantly impacting NF-κB and TNF (tumor necrosis factor) signaling pathways." (PMID 39769099, 2024). "TNF binds to its ligand TNFR1 to activate the NF-kB pathway, which is highly activated in the mesenchymal subtype of glioma." (PMID 38561856, 2024). "Furthermore, TNF did not cause chemoresistance in any of the examined glioma cell lines." (PMID 38561856, 2024). "SRGN-expressing glioma cells after co-culture with mast cells further enhance their expression of SRGN, CD44, CXCL-10, CXCL-12 and TNFα as well as EMT-related genes ZEB-1 and vimentin." (PMID 38672477, 2024). "Fucoidan suppressed tumor necrosis factor-alpha (TNF-alpha)- and interferon-gamma (IFN-gamma)-induced NO production and iNOS expression in C6 glioma cells." (PMID 39744139, 2024). "And in our study, we found that the mRNA expression levels of IL-6, TNF-α, and STAT3, which are important factors in the STAT3 signaling pathway, were significantly increased in glioma samples." (PMID 38495483, 2024). "It has also revealed that TLR-4 activation (1 μg/ml) stimulates the secretion of the inflammatory cytokines (TNFα and ILs) and up-regulation of specific stem cell markers, including CD34 and CD133 in human glioma U251 cells." (PMID 38698968, 2024). "Different signaling pathways have been suggested to play an important role in the proneural-to-mesenchymal subtype transition of gliomas including cytokines IL6, TGFβ, and TNFα." (PMID 38632238, 2024). "Various inflammatory cytokines, including TNF, CSF2, IL1A, IL17A, IL6, and IFNG, were predictively inhibited in glioma samples exhibiting high CSMD1 expression." (PMID 38561856, 2024).
glioma (continued). "Abrogated USP7 expression promotes CD8+ T cell proliferation, elevates tumor necrosis factor (TNF) alpha and interferon gamma (IFN-γ) levels, and inhibits glioma cell immune evasion, which can be reversed by PD-L1 overexpression." (PMID 37415977, 2023). "In vitro treatment of two glioma cell lines, LN229 and U251, with EGFR-CAR NK-cells infected with OV-IL15C significantly increased IFN-γ and TNF-α production." (PMID 38136398, 2023). "Tumor necrosis factor-alpha (TNF-α) and Interleukin-1 beta (IL-1β) can induce the production of the small heat shock protein, CRYAB (HspB5) in U373 glioma cells, and U373-secreted exosomes." (PMID 37373314, 2023). "Flow cytometry and qRT‒PCR results showed that CD8+ T cells cocultured with M2‐Exos‐cultured glioma cells showed lower proliferation and expression of IFN‐γ, TNF‐α, and Gzmb." (PMID 37097629, 2023). "Of course, the M1-type of TAMs secrete interleukin-1β (IL-1β) and tumor necrosis factor (TNF-α) to promote T cell activation to kill glioma cells, but this effect is minimal in the glioma microenvironment." (PMID 37375698, 2023). "Gene sets for activated macrophages, including nitric oxide synthase (NOS) production, inflammatory response and tumor necrosis factor (TNF-α) signaling, were also enriched in the macrophage cluster from gliomas in WT mice." (PMID 36266311, 2022). "Co-culture of mast cells with glioma cells induces the expression of serglycin, CD44, ZEB1, vimentin, CXCL10, CXCL12, and TNF-α in glioma cells and IL-6 and CXCL1 in mast cells, creating an inflammatory milieu that induce glioma cell aggressiveness." (PMID 35494005, 2022). "CD44 knock-out in myeloid cells affected their ability to upregulate TNF-α and IL-1b, and most notably, to increase MMP9 production in response to gliomas." (PMID 35992852, 2022). "The expression of proinflammatory cytokines such as TNF-α, IL-6 and IL-1β induced by LPS treatment was dose-dependently attenuated in IOE-treated C6 glioma cells." (PMID 36670940, 2022). "TNF-α is involved in activation of the NF-kB and PI3K-Akt signalling pathways, and ANXA1 regulates the proliferation, migration, and invasion of glioma cells via PI3K/AKT signalling." (PMID 35415239, 2022). "qRT-PCR assay demonstrated the upregulation of TNF-α, IL-2, IL-3, and IL-4 expression, whereas the downregulation of IL-12 expression in HK2-knockdown glioma cells, suggesting that HK2 is essential for glioma development through regulating immune infiltration." (PMID 35982398, 2022). "In G422 murine glioma models, it has been shown that PDT increases the ratio of CD4+/CD8+ lymphocytes and promotes TNF-α and IFN-γ release and promotes an anti-glioma response mediated by complement C3 and T-cells." (PMID 33540759, 2021). "Cytokines such as IL-6, TGF-β, IL-10 and IL-4 dominate over inflammatory TNF-α, IL-12 and IL-2; and the NFkB signaling pathway stimulated by TNF-α is significantly downregulated in high-grade gliomas." (PMID 34949203, 2021). "In glioma TME, TNF-α promotes tumor formation and angiogenesis, and induces neovascularization through VEGF and IL-8." (PMID 33806300, 2021). "Inhibition of TNFα blocks GAM-induced EC activation both in vitro and in vivo and improve survival in mouse glioma models." (PMID 33853689, 2021). "The three most important luteolin-related signaling pathways in the glioma setting include the hsa04010: MAPK-signaling pathway, the hsa04151: PI3K-Akt signaling pathway, and the hsa04668: TNF signaling pathway." (PMID 34873410, 2021). "Use of adenovirus expressing TNFα or IFNγ into tumors enhanced infiltration of CD4+ and CD8+ T cells along with increased expression of MHCI/II on the glioma cells in vivo." (PMID 33790740, 2021). "Activation of NLRP3 expression by S100A8/S100A9 inhuman PBMCs increased the secretion of pro-inflammatory cytokines (IL-6, IL-1β, TNFα) and chemokines (IL-8, Gro-α, MIP-1α/β) that are prevalent in gliomas." (PMID 34975408, 2021).